PINX1 (PIN2 (TERF1) interacting telomerase inhibitor 1)
Diseases named in the same sentence as PINX1 in open-access papers (continued):
Sharing a sentence is not in itself a finding about the gene and the disease.
cancer (continued). "Our findings suggest that PinX1 may facilitate the invasion and migration of malignant tumors." (PMID 30079348, 2018). "Furthermore, the mechanism of PinX1 may change in response to chemoradiotherapy, which may influence the prognosis of patients with malignant tumors." (PMID 30079348, 2018). "Low PINX1 expression was associated with poor OS and DFS/RFS and lymphatic invasion and advanced tumor-node-metastasis stage, suggesting that PINX1 expression may be a useful predictor of prognosis in patients with malignant tumors." (PMID 30079348, 2018). "Therefore, the precise prognostic role of PINX1 in malignant tumors remains controversial." (PMID 30079348, 2018). "However, the tumour-suppressive roles of PinX1 in different types of human cancers are unclear." (PMID 28815183, 2017). "Furthermore, emerging evidence suggest that PinX1 (especially its TID domain) might be a potential new target cancer treatment." (PMID 27556185, 2016). "Moreover, emerging evidence suggest that PinX1 (especially its TID domain) might be a potential new target cancer treatment." (PMID 27556185, 2016). "Thus, LOH seems play a major role in the inactivation of PinX1 in human cancers." (PMID 27556185, 2016). "Notably, most tumors in PinX1+/- mice are epithelial carcinomas arising in organs that are known to develop common cancers in humans, including lung, mammary, liver and gastrointestinal tract cancers, which are also known to have frequent LOH at 8p23 in humans." (PMID 22021332, 2011). "Moreover, emerging evidence suggest that PinX1 and especially its small telomerase inhibitory domain might be a potential new drug target for treat cancers that have telomerase activation." (PMID 22021332, 2011). "Moreover, 20% of PinX1+/- mice developed two or three cancer types within the same animals." (PMID 22021332, 2011). "Notably, PinX1 gene localizes to human chromosome 8p23, which is one of the regions that experiences the most frequent loss of heterozygosity (LOH) in many common human cancers." (PMID 22021332, 2011). "PinX1, known as a potent TERT inhibitor, also contributes to cellular aging and cancer tumorigenicity." (PMID 35847001, 2022). "However, the role of PinX1 in telomerase/telomere regulation and cancer remains unclear." (PMID 24940406, 2014). "Some cancer-related genes are located in these highly common, early appearing RARs: MCL1, CTSK, ARNT, S100A10, PTK2, PTP4A3, and PSCA in the RAR-Gs; and DLC1, PINX1, and GATA4 in the RAR-Ls." (PMID 22938721, 2012). "However, many questions remained to be addressed including how PinX1 regulates chromosome stability and tumorigenesis, how PinX1 is regulated under physiological and pathological conditions, how to develop PinX1-based cancer therapy, and whether PinX1 has other new functions." (PMID 22021332, 2011). "PinX1 is a TRF-binding protein, and it was reported in various cancers." (PMID 35847001, 2022). "The pooled results of the meta-analysis showed that low PINX1 expression was associated with significantly poorer OS and DFS/RFS, but not DSS, in patients with malignant tumors." (PMID 30079348, 2018). "Therefore, we conducted a meta-analysis to determine whether PINX1 expression is associated with overall survival (OS), disease-specific survival (DSS), disease-free survival (DFS), recurrence-free survival (RFS), and clinicopathological characteristics in patients with malignant tumors." (PMID 30079348, 2018). "It is the first time to validate PinX1 involves in regulating cancer metastasis independent of its ordinary roles like maintaining telomerase activity, the length of telomerase and chromosome stability." (PMID 26033551, 2015).
cancer (continued). "In the study by Zhou and Lu, downregulation of PinX1 expression via antisense cDNA transfection resulted in increased telomerase activity, increased telomere length and enhanced tumor malignancy in the HT1080 (telomerase-positive) cancer cell line." (PMID 24940406, 2014). "We have originally shown that whereas reducing PinX1 in human cancer cells increases their tumorigenicity, overexpression of PinX1, especially its small TID domain (telomerase-inhibitory domain) drives cancer cells into crisis and potently suppresses their ability to form tumors in mice." (PMID 22021332, 2011). "The mechanism for PinX1 gene inactivation in human cancers is not clear." (PMID 27556185, 2016). "Initially, when PinX1 was isolated, Zhou and Lu reported that the gene was located on human chromosome 8p23.1, which is a region that frequently exhibits LOH in many human cancers, and that the depletion of endogenous PinX1 increased the tumorigenicity of HT1080 cells in nude mice." (PMID 24672800, 2014). "For the cancer phenotypes, the reverse genetics models were enriched in DNA repair functions (p = 2×10−5, FDR p = 0.03) (POLG/FANCI, SLX4/FANCP, XRCC1, BRCA1, FANCA, CHD1L) while the additive model showed enrichment related to chromatid segregation (p = 4×10−6, FDR p = 0.005) (KIF25, PINX1)." (PMID 24349080, 2013). "Overexpression of PinX1 in tumor cells could inhibit telomerase activity, shorten telomeres, and suppress tumor growth, while depletion of endogenous PinX1 increased telomerase activity, elongated telomeres, and enhanced tumorigenicity in telomerase-positive HT1080 cancer cells." (PMID 24268029, 2013). "The absence of PINX1 rendered Hela cells susceptible to PARP inhibitors, a phenomenon not only confirmed in OVCAR8, OC316, and BEL7404 cancer cell lines but also validated in vivo in xenograft mouse models, suggesting PINX1 as a potential target for cancer therapy." (PMID 39174499, 2024). "Moreover, there is no genetic evidence for any involvement of PinX1 in cancer." (PMID 22021332, 2011). "However, the role of PinX1 in telomerase regulation and cancer development is not clear." (PMID 22021332, 2011).
tumor (33 papers, 2007 to 2025). "Tumor size was monitored, and the results showed that PINX1 deficient tumors are significantly more sensitive to Talazoparib treatment compared to the PINX1 proficient tumors, suggesting a promising translational possibility." (PMID 39174499, 2024). "Low PINX1 expression was also associated with lymphatic invasion (OR: 2.23, 95.0% CI: 1.35–3.70; P = 0.002) and advanced tumor-node-metastasis stage (OR: 2.43, 95.0% CI: 1.29–4.57; P = 0.006)." (PMID 30079348, 2018). "PIN2-interacting protein 1 (PinX1), a nucleolar protein associated with telomere/telomerase, is a putative tumor suppressor." (PMID 24940406, 2014). "Our findings suggested that PinX1 could be a potential tumour suppressor in NSCLC and that loss of PinX1 promoted NSCLC progression." (PMID 28815183, 2017). "Because low PinX1 expression is associated with poor prognosis, supporting PinX1 may play important roles in one or more steps of tumor metastasis." (PMID 25888829, 2015). "Depletion of PinX1 impairs rDNA transcription, compromises ribosome biogenesis and inhibits tumor cells proliferation." (PMID 40639785, 2025). "PIN2/TRF1-interacting telomerase inhibitor 1 (PinX1) functions as a telomerase inhibitor and tumor suppressor." (PMID 39634130, 2025). "Compared to radioimmunotherapy alone, silencing PinX1 combined with radioimmunotherapy significantly increased the infiltration of CD8+ T cells in tumor tissues (p = 0.0376)." (PMID 38431575, 2024). "Our study found that silencing PinX1 combined with IR significantly increased CD8+ T cells infiltration as well as CD8+ cytotoxic T lymphocytes in tumor tissues and peripheral immune organs." (PMID 38431575, 2024). "In our study, silencing PinX1 in combination with radioimmunotherapy significantly reduced the proportion of Tex in tumor tissues." (PMID 38431575, 2024). "PinX1 was initially thought to inhibit the activity of telomerase through its binding to telomerase, which is considered a tumor suppressor." (PMID 38431575, 2024). "The human PINX1 gene is a telomerase inhibitor and putative tumor suppressor gene that inhibits telomerase activity and shortens the length of telomeres to suppress tumor growth." (PMID 30079348, 2018). "PINX1 is a putative tumour suppressor and overexpression of PINX1 inhibits telomerase activity, shortens telomeres and induces crisis." (PMID 28233473, 2017). "In the present study, we also provided evidence of the tumour-suppressive role of PinX1 in NSCLC cells." (PMID 28815183, 2017). "This variation suggests that abnormal gene regulation and/or protein functions of PinX1 in tumorigenesis are complicated and are likely to be tumor-type-specific." (PMID 28372542, 2017). "Because PinX1 was found to function as a tumour suppressor, we attempted to confirm our previous findings in NSCLC cells." (PMID 28815183, 2017). "In the present study, we enrolled a total of 158 patients with NSCLC and used IHC to detect PinX1 protein expression in tumour tissues." (PMID 28815183, 2017). "It has been reported that PinX1 suppress tumor growth and depletion of endogenous PinX1 can enhance tumorigenicity." (PMID 28978030, 2017). "It has been reported that PinX1 suppress tumor growth and depletion of endogenous PinX1 enhanced tumorigenicity." (PMID 28372542, 2017). "Recent results have discovered that PinX1 is a major tumor suppressor and involved in tumorigenesis and tumor progression." (PMID 27556185, 2016). "PinX1 levels were inversely correlated with tumor multiplicity, advanced N classification, high proliferation index (Ki-67), and poor survival." (PMID 27556185, 2016). "Our data demonstrated that PinX1 expression was dramatically decreased in ccRCC tissues compared with normal renal tissues and paired adjacent non-tumor tissues." (PMID 26033551, 2015).
tumor (continued). "Our data showed that PinX1 expression was apparently decreased in ccRCC tissues compared with normal renal tissues and paired adjacent non-tumor tissues." (PMID 26033551, 2015). "In training cohort TMA slide containing 75 cases ccRCC tissues with paired adjacent non-tumor tissues, we observed that a significantly lower expression of PinX1 in tumor tissues compared with paired adjacent non-tumor tissues (P < 0.001)." (PMID 26033551, 2015). "Taken together, PinX1 expression is decreased in ccRCC tissues compared with paired adjacent non-tumor tissues and normal renal tissues." (PMID 26033551, 2015). "We performed a univariate Cox regression analysis including PinX1 expression, age, tumor size, pT status, pN status, and TNM stage to study the effects of PinX1 on patients’ survival in ccRCC." (PMID 26033551, 2015). "PinX1 (PIN2/TRF1-interacting telomerase inhibitor 1) was suggested to be correlated with tumor progression." (PMID 25888829, 2015). "Due to migration and invasion ability is crucial for tumor metastasis, we examined the effects of PinX1 on migration and invasion of ccRCC cells." (PMID 26033551, 2015). "PIN2/TRF1-interacting telomerase inhibitor 1 (PinX1) is a novel cloned gene which has been identified as a major haploinsufficient tumor suppressor essential for maintaining telomerase activity, the length of telomerase and chromosome stability." (PMID 26033551, 2015). "PinX1 is a potent telomerase inhibitor and a putative tumor suppressor, firstly found as a Pin2/TRF1-binding protein." (PMID 25888829, 2015). "The potent tumor suppressor PinX1 was originally isolated as one of the Pin2/TRF1 interaction proteins." (PMID 24672800, 2014). "Pin2/TRF1 binding protein X1 (PinX1) has been identified as an endogenous telomerase inhibitor and a major haploinsufficient tumor suppressor gene." (PMID 24936151, 2014). "Certain studies consider PinX1 to be an intrinsic telomerase/telomere inhibitor and a putative tumor suppressor, as it binds to and suppresses telomerase enzymatic activity." (PMID 24940406, 2014). "PinX1 levels were inversely correlated with tumor multiplicity, advanced N classification, high proliferation index (Ki-67), and poor survival (P < 0.05)." (PMID 24268029, 2013). "PinX1 levels were inversely correlated with tumor multiplicity and advanced N classification (P < 0.05)." (PMID 24268029, 2013). "Originally, PinX1 was identified as an intrinsic telomerase inhibitor and a putative tumor suppressor because of its binding to and inhibition of telomerase." (PMID 24268029, 2013). "Recently, it has been reported that human PinX1 can regulate telomerase activity and suppress tumor growth both in vivo and in vitro." (PMID 24268029, 2013). "PinX1 has been identified as a critical component in regulating telomerase activity, and is proposed to be a putative tumor suppressor." (PMID 24268029, 2013). "Human interacting protein X1 (PinX1) has been identified as a critical telomerase inhibitor and proposed to be a putative tumor suppressor gene." (PMID 22316341, 2012). "Some studies have found that PinX1 can attenuate telomerase activity, inhibit growth of tumor cells and induce apoptosis." (PMID 22316341, 2012). "PinX1 has been identified as a major tumor suppressor, essential for telomerase activity and maintaining chromosome integrity." (PMID 22727333, 2012). "Pin2/TRF1 interacting protein X1 (PinX1) was recently found as a tumor suppressor and telomerase inhibitor in vivo." (PMID 22316341, 2012). "To better understand the role of PinX1 on tumor cells, we also successfully established PinX1-specific siRNA PinX1-FAM-siRNA, transfection of which significantly silenced 70% of endogenous PinX1 mRNA in NPC cells (p < 0.001)." (PMID 22316341, 2012). "Overexpression of LPTS/PinX1 could inhibit the tumor cell growth in the colorectum, breast, liver, stomach and lung, etc.." (PMID 40896430, 2025).
tumor (continued). "Tumor type specificity and posttranslational modification of PinX1 may elucidate its duality in regulating cell growth." (PMID 40639785, 2025). "Here, we report the molecular basis of the tumor suppression function of PinX1." (PMID 39634130, 2025). "We found that silencing PinX1 combined with IR significantly inhibited tumor growth mean tumor volume on day 16 ± SEM: 930.2 ± 107.2 mm3 IR vs. 649.1 ± 44.3 mm3 shPinX1 plus IR, p = 0.0421) and dramatically improved the survival of the homograft mouse(p = 0.049)." (PMID 38431575, 2024). "For NSCLC, previous studies have shown that PinX1 inhibits tumor cell proliferation." (PMID 38431575, 2024). "However, many studies have suggested that PinX1 positively regulates telomere maintenance and promotes genome stability in tumor cells." (PMID 38431575, 2024). "In the in vitro experimental part of our study (including colony formation assay and CCK-8 assay), knockdown of PinX1 also increased cell proliferation of tumor cells to a certain extent, however, when combined with RT, cell proliferation appeared significantly downregulated relative to RT alone." (PMID 38431575, 2024). "The anti-tumour effects of Rec8 are caused by downregulation of cell growth-related genes (G6PD, SLC2A1, NOL3, MCM2, SNAI1, and SNAI2) and also by upregulation of both apoptosis or migration inhibitors (Gadd45G and LDHA) and tumour inhibitors (PinX1, IGFBP3, and ETS2)." (PMID 36139540, 2022). "These tumours also exhibited an increase in E-cadherin expression and a reduction in Vimentin expression in xenografts derived from PinX1 overexpression nasopharyngeal CD133+ CSCs, while the expression levels were reversed by co-inhibition of miR-200b via immunohistochemistry." (PMID 32028978, 2020). "Since its discovery as a potent telomerase inhibitor in 2001, PinX1 had been revealed to be involved in tumorigenesis and tumor progression, and evidence suggested that its functions could be tumor-type-specific." (PMID 31210926, 2019). "Second, the genetic background of PINX1 may be different in different types of tumors and the role of PinX1 in tumorigenesis complicated and may be tumor type-specific." (PMID 30079348, 2018). "The telomerase/telomere interacting protein PinX1 has been suggested as a tumor suppressor." (PMID 28372542, 2017). "Since PinX1 is a putative tumor suppressor, we next sought to determine whether it could serve as an indicator for patient survival." (PMID 28978030, 2017). "In addition, the pattern of PinX1 genetic expression is vastly different in various tissues and tumor types." (PMID 28978030, 2017). "The remaining copy number contains insufficient PinX1 for full inhibition of telomerase activity, which could immortalize the tumor and result in telomere lengthening." (PMID 28978030, 2017). "However, research has shown that PinX1 can have opposing molecular status in its expression patterns in several other tumor types." (PMID 28978030, 2017). "The status of PinX1 genetic alterations was correlated with prognosis and may be tumor-type specific." (PMID 28978030, 2017). "This was done to better understand the potential role played by PinX1 in tumor development." (PMID 28978030, 2017). "Finally, HSP90AA1 was also shown to interact with PinX1, which mainly participates in stabilizing many proteins required for tumor growth." (PMID 28978030, 2017). "Together all of these results indicate that PinX1 is a major tumor suppressor." (PMID 27556185, 2016). "These suggest that the abnormalities and/or functions of PinX1 in tumour genesis and progression are complicated and may be tumor-type-specific." (PMID 27556185, 2016). "The results of the present study support the hypothesis that combined therapy with PinX1-siRNA/DOX can successfully maintain the tumor inhibition effect with reduced side effects." (PMID 24940406, 2014).